VPS33A (VPS33A core subunit of CORVET and HOPS complexes)
Description:
Plays a role in vesicle-mediated protein trafficking to lysosomal compartments including the endocytic membrane transport and autophagic pathways. Believed to act as a core component of the putative HOPS and CORVET endosomal tethering complexes which are proposed to be involved in the Rab5-to-Rab7 endosome conversion probably implicating MON1A/B, and via binding SNAREs and SNARE complexes to mediate tethering and docking events during SNARE-mediated membrane fusion. The HOPS complex is proposed to be recruited to Rab7 on the late endosomal membrane and to regulate late endocytic, phagocytic and autophagic traffic towards lysosomes. The CORVET complex is proposed to function as a Rab5 effector to mediate early endosome fusion probably in specific endosome subpopulations. Required for fusion of endosomes and autophagosomes with lysosomes; the function is dependent on its association with VPS16 but not VIPAS39. The function in autophagosome-lysosome fusion implicates STX17 but not UVRAG.
Synonyms: MPSPS
Tractability: Small molecule: a structure with a bound ligand is known. Antibody: UniProt places it where antibodies can reach, with high confidence. PROTAC: ubiquitination databases record sites on it; its protein half-life has been measured.
Gene: Protein-coding gene on chromosome 12 (122,229,564 to 122,266,502, reverse strand). Ensembl gene ENSG00000139719.
Subcellular location: Cytoplasmic vesicle; Late endosome membrane; Lysosome membrane; Early endosome; Cytoplasmic vesicle, autophagosome; Cytoplasmic vesicle, clathrin-coated vesicle
Subcellular location (Human Protein Atlas): Nucleoplasm
Pathways (Reactome):
Disease: SARS-CoV-2 modulates autophagy
Gene Ontology:
Molecular function: molecular adaptor activity; protein binding
Biological process: autophagosome maturation; autophagosome-lysosome fusion; endosome to lysosome transport; lysosome localization; melanosome localization; vesicle-mediated transport; endosomal vesicle fusion; platelet formation; regulation of developmental pigmentation; regulation of SNARE complex assembly; developmental pigmentation
Cellular component: AP-3 adaptor complex; clathrin complex; early endosome; HOPS complex; late endosome; lysosomal membrane; perinuclear region of cytoplasm; autophagosome; CORVET complex; cytoplasmic vesicle; endosome membrane; lysosome; clathrin-coated vesicle; late endosome membrane
Genetic constraint (gnomAD): Loss-of-function variants: 29 observed, 67.85 expected, observed/expected ratio (o/e) 0.43, 90% interval 0.32 to 0.58. The upper end of that interval is the gene's LOEUF score, 0.58, which puts it in group 2 of 6, group 1 being the genes least tolerant of losing a copy. Missense variants: 605 observed, 759.94 expected, observed/expected ratio (o/e) 0.8, 90% interval 0.74 to 0.85. Synonymous variants: 300 observed, 299.3 expected, observed/expected ratio (o/e) 1, 90% interval 0.91 to 1.1.
Gene-disease validity (ClinGen):
ClinGen rates the evidence that VPS33A causes each of these diseases.
mucopolysaccharidosis-plus syndrome (autosomal recessive): Definitive.
Homologues: Orthologues: chimpanzee VPS33A (100% identical), macaque VPS33A (100% identical), guinea pig VPS33A (99% identical), dog VPS33A (98% identical), mouse Vps33a (98% identical), pig VPS33A (98% identical), rabbit VPS33A (97% identical), rat Vps33a (97% identical), tropical clawed frog vps33a (87% identical), zebrafish vps33a (84% identical), Drosophila melanogaster car (45% identical), Caenorhabditis elegans vps-33.1 (27% identical). Paralogues in human: VPS33B (34% identical), STXBP2 (17% identical), VPS45 (16% identical), STXBP3 (16% identical), SCFD1 (15% identical), SCFD2 (12% identical).
Diseases named in the same sentence as VPS33A in open-access papers:
VPS33A is named in the same sentence as 30 diseases in open-access papers, as found by Europe PMC text mining. Sharing a sentence is not in itself a finding about the gene and the disease. The quoted sentences say what the papers report.
mucopolysaccharidosis (6 papers, 2019 to 2025). A group of autosomal recessive or X-linked inherited lysosomal storage disorders affecting the metabolism of mucopolysaccharides, resulting in the accumulation of mucopolysaccharides in the body. "Whole exome sequencing identified a novel VPS33A mutation in a patient suffering from a variant form of mucopolysaccharidosis." (PMID 36153662, 2022). "Mucopolysaccharidosis-Plus Syndrome (MPSPS), an autosomal recessive disease caused by a mutation in the endo-lysosomal tethering protein VPS33A, shows additional renal and hematopoietic abnormalities (“Plus symptoms”) uncommon in conventional MPS." (PMID 35628659, 2022). "Of note, two patients have been lately reported with an overlapping phenocopy of mucopolysaccharidosis plus disease caused by genetic deficiency of VPS16, another subunit of the HOPS and CORVET tethering complexes to which VPS33A is recruited by binding." (PMID 36153662, 2022). "While reporting a case displaying mucopolysaccharidosis plus, a rare and attenuated subtype of mucopolysaccharidosis related to the VPS33A protein, Pavlova and co-workers described the effects of bortezomib and eliglustat in improving glycosphingolipid trafficking in patient-derived fibroblasts." (PMID 38540351, 2024). "The occurrence of an attenuated VPS33A defect reported here for the first time in a young adult with late onset mucopolysaccharidosis plus disease and slowly progressive course limited to the skeletal system with psychomotor delay, clearly indicates a better prognosis for survival." (PMID 36153662, 2022). "From the practical aspect, it is of paramount importance in the diagnosis of suspected lysosomal diseases with features of mucopolysaccharidosis, that advanced and sensitive methods for GAG analysis are used and that genetic studies should include VPS33A in relevant diagnostic panels." (PMID 36153662, 2022).
mucopolysaccharidosis-plus syndrome (4 papers, 2022 to 2023). "Mucopolysaccharidosis-Plus Syndrome (MPSPS) is a severe autosomal recessive disease caused by a mutation in the vacuolar-protein-sorting-associated protein 33A (VPS33A) gene." (PMID 35628659, 2022). "Mucopolysaccharidosis-plus syndrome (MPS-PS) is a novel autosomal recessive disorder caused by a mutation in the VPS33A gene." (PMID 35327996, 2022).
Lysosomal disease (2 papers, 2019 to 2022). "In a separate study, two siblings born into a consanguineous Turkish family had been described with similar features of a lysosomal disease and also harboured the same mutation in the VPS33A gene." (PMID 31070736, 2019).
melanoma (2 papers, 2014 to 2023). A malignant, usually aggressive tumor composed of atypical, neoplastic melanocytes. "VPS of melanoma cells with deletion of VPS33A or cappuccino protein (CNO) caused an increase in cis‐diaminedichloroplatinum II nuclear localization, DNA platinization damage, and apoptosis, thus improving the sensitivity of therapy." (PMID 37249275, 2023).
tuberculosis (2 papers, 2019 to 2022). A chronic, recurrent infection caused by the bacterium Mycobacterium tuberculosis. "In addition, an inverse correlation between VPS33A and miR-423-5p was found in peripheral blood mononuclear cells of patients with tuberculosis." (PMID 30898038, 2019). "A recent study showed that the expression of miRNA-423 was significantly increased in the serum of patients with tuberculosis, and the upregulation of miR-423-5p could suppress autophagosome–lysosome fusion in macrophages by posttranscriptional regulation of VPS33A." (PMID 35309115, 2022). "Since the inhibition of autolysosome formation plays a critical role in tuberculosis occurrence, our findings suggests that miR-423-5p could suppress autophagosome–lysosome fusion by post-transcriptional regulation of VPS33A, which might be important for the occurrence of active tuberculosis." (PMID 30898038, 2019).
cardiomyopathy (1 paper, 2021). A disease of the heart muscle or myocardium proper. "For example, VPS33A patients suffer from renal dysfunction and cardiomyopathy, which we have not observed in our patients (although a sibling to one patient reportedly died from cardiac complications of unknown cause)." (PMID 33938619, 2021).
Cholestatic liver disease (1 paper, 2023). "Interestingly, pathogenic variants in several components of the endosomal system (e.g., in VP16 and VPS33A) cause cholestatic liver disease in humans that is accurately modeled by loss-of-function mutations in the zebrafish." (PMID 37490339, 2023).
GM1 gangliosidosis (1 paper, 2019). A rare lysosomal storage disorder characterized biochemically by deficient beta-galactosidase activity and clinically by a wide range of variable neurovisceral, ophthalmological and dysmorphic features. "Delayed myelination and calcification of basal ganglia, as seen in patients with Krabbe disease and GM1 gangliosidosis, had been previously noted in Yakut patients with mutated VPS33A." (PMID 31070736, 2019).
Hermansky-Pudlak syndrome (1 paper, 2022). Hermansky-Pudlak syndrome (HSP) is a multi-system disorder characterized by oculocutaneous albinism, bleeding diathesis and, in some cases, neutropenia, pulmonary fibrosis, or granulomatous colitis. "Melanosome biogenesis is mediated by VPS33A and not VPS33B, and VPS33A mutations impair melanosome biogenesis in the Hermansky-Pudlak syndrome." (PMID 36429129, 2022).
Obesity (1 paper, 2018). Accumulation of substantial excess body fat. "Instead, our screen suggests that different nearby cis gene may be more fruitful for further functional follow up for obesity, namely ZCCHC8, VPS33A, RSRC2; SPDEF, NUDT3; SETD1, VKORC1; SGSM2, SRR; VASP, SIX5; OTX1; BANK1; ARIH1; ELL; CHST8, respectively." (PMID 29608557, 2018).
infection (2 papers, 2014 to 2022). The state of being infected such as from the introduction of a foreign agent such as serum, vaccine, antigenic substance or organism. "Patients with the infantile VPS33A‐related disease died with multisystem failure triggered by infection within the first six years of life." (PMID 36153662, 2022).
tumor (1 paper, 2023). "Frameshift mutations in VPS33A may result in protein truncation and alter the interaction with the tumor suppressor UVRAG." (PMID 37249275, 2023).
VPS33A also shares sentences with these, for which no sentence is quoted: anemia (1 paper); asthma (1); cancer (1); cardiac disease (1); Chédiak−Higashi syndrome (1); Failure to thrive (1); Immunodeficiency (1); Intellectual disability (1); joint effusion (1); Krabbe disease (1); lysosomal storage disease (1); neutropenia (1); ovarian carcinoma (1); renal disease (1); renal dysfunction (1); renal failure (1); Splenomegaly (1); Thrombocytopenia (1).